MMP7 (matrix metallopeptidase 7)
Diseases named in the same sentence as MMP7 in open-access papers (continued):
Sharing a sentence is not in itself a finding about the gene and the disease.
pulmonary fibrosis (continued). "MMP-7 is considered a profibrotic molecule, and reports indicate that is increased in patients with idiopathic pulmonary fibrosis as well as in the serum of other interstitial lung diseases and even in asymptomatic individuals with interstitial lung abnormalities." (PMID 39624381, 2024). "The negative association between MMP7 and lung fibrosis in this study was unexpected, potentially driven by outliers or patient-specific factors that were not discernible." (PMID 37075981, 2023). "It is suggested that circulating levels of MMP-7 are related to idiopathic pulmonary fibrosis." (PMID 37372128, 2023). "Hence, circulating MMP-7 levels were described as a potential biomarker of COVID-19 severity and potential peripheral blood biomarkers related to idiopathic pulmonary fibrosis." (PMID 37372128, 2023). "The matrix metalloproteinase (MMP) family, mainly MMP7 is involved in lung fibrosis." (PMID 37029197, 2023). "In addition, YJT not only decreased airway wall thickness, average alveolar intercept, and lung fibrosis, but it also suppressed the expression of matrix metallopeptidase (MMP)-7, MMP-9, and transforming growth factor-B (TGF-β) and collagen deposition." (PMID 35035511, 2022). "MMP-7 is also a validated biomarker for idiopathic pulmonary fibrosis severity that correlates with pulmonary function, and our findings suggest that MMP-7 may be a novel biomarker of COVID-19 ARDS recovery." (PMID 34111030, 2021). "Elevated MMP-7 levels are also detected in the peripheral blood of patients with human idiopathic pulmonary fibrosis (IPF) and may be used as a biomarker for predicting disease progression and death." (PMID 32630493, 2020). "MMP-7 induction by RSPO3 could be an important mechanism by which RSPO3 promotes lung fibrosis, which deserves further study." (PMID 32160239, 2020). "MMP-7 knockout (KO) mice were shown to be protected from bleomycin (BLM)-induced lung fibrosis." (PMID 32053892, 2020). "MMP-7, a Wnt target gene, has been shown to play an important role in lung fibrosis." (PMID 32160239, 2020). "We described how MMP-7 is involved in other pathologies such as renal and pulmonary fibrosis and if these mechanisms could be extrapolated to the pathogenesis of BA." (PMID 33409288, 2020). "sFasL may be an unrecognized mechanism for MMP-7-mediated decreased tissue regeneration following injury and the evolution of lung fibrosis." (PMID 32053892, 2020). "In contrast, MMP-7 carries out both pro- and antifibrotic functions in lung fibrosis." (PMID 31511015, 2019). "However, increased levels of MMP-7 have been shown in aberrant healing processes such as pulmonary fibrosis, especially in patients with idiopathic pulmonary fibrosis, where the levels of MMP-7 seem to correlate with disease severity and prognosis." (PMID 28634370, 2017). "Moreover, MMP-7 knockout mice are protected from bleomycin-induced lung fibrosis, indicating that MMP-7 actively participates in the tissue fibrotic response." (PMID 27293304, 2016). "Moreover, it has been reported that mice lacking MMP-7 are protected from bleomycin-induced lung injury suggesting a key role of MMP-7 in the induction of pulmonary fibrosis by bleomycin." (PMID 24396596, 2013). "Indeed, levels of MMP-2 and MMP-9 protein and MMP7 mRNA are elevated in the lungs of patients with human idiopathic pulmonary fibrosis (IPF) and MMP-13 expression is increased in the lungs of patients with chronic obstructive pulmonary disease (COPD)." (PMID 23593124, 2013). "Among SSc patients, higher levels of serum MMP-7 were seen in patients with lung fibrosis compared to those without and were associated with lower DLCO levels, although the association of MMP-7 levels with ILD progression was not evaluated." (PMID 22988462, 2012).
pulmonary fibrosis (continued). "Notably, patients with lung fibrosis and concomitant pulmonary hypertension had higher mean MMP-7 serum levels compared to those with lung fibrosis alone, indicative of the potential confounding issue of underlying vasculopathy in DLCO reduction." (PMID 22988462, 2012). "Using a combined set of scoring systems they determined that matrilysin (matrix metalloproteinase-MMP-7), a metalloprotease not previously associated with pulmonary fibrosis, was the most informative increased gene in their data set." (PMID 15585067, 2004). "However, our group found an increase in serum biomarkers of pulmonary fibrosis (MMP7, MMP1, and periostin) in patients with early fibrotic changes in chest CT at 2 months after hospital discharge, not only in IMV patients but also in those treated with conventional or high flow nasal cannula oxygen." (PMID 36096801, 2022). "Therefore, the function of MMP7 may be pleiotropic in pulmonary fibrosis, attributed to its various biological functions related to apoptosis, inflammation, fibroproliferation, and innate immunity." (PMID 33672678, 2021). "Also, as has been reported by others, pulmonary fibrosis patients show elevated levels of MMP-7." (PMID 24396596, 2013). "MMP-7 inhibitor intervention reduced collagen deposition and structural damage, and MMP-7 inhibitor attenuated the CFA-induced pulmonary fibrosis score." (PMID 40722657, 2025). "In idiopathic pulmonary fibrosis (IPF) patients, serum MMP7 levels were higher at baseline (pre‐treatment) and at 1 year of antifibrotic treatment in those with progressive disease, compared to those with stable disease." (PMID 39919729, 2025). "BLM induced a significant increase in all assessed markers of lung fibrosis: hydroxyproline (HYP), proCollagenI, WNT1-inducible-signaling pathway protein 1 (WISP-1), and matrix metalloproteinase-7 (MMP7)." (PMID 41515944, 2025). "In vivo, CFA induced arthritis and subpleural lung inflammation in rats, but the MMP-7 inhibitor and MMP-7 siRNA attenuated CFA-induced lung inflammation and subpleural lung fibrosis." (PMID 40722657, 2025). "Consistent with previous research, it is recognized that heightened MMP7 and α-SMA expression contributes to the advancement of pulmonary fibrosis." (PMID 38575860, 2024). "MMP-7 synthesis is raised in clinical IPF and preclinical models for lung fibrosis, whereas MMP-7 knockout rodents display diminished fibrotic reactions." (PMID 38803919, 2024). "Proinflammatory cytokines in SARS-CoV-2 infection are also believed to increase matrix metallopeptidase 1 (MMP1) and MMP7 expression, which degrades the ECM and contributes to airway remodeling and pulmonary fibrosis." (PMID 37893011, 2023). "Matrix metalloproteinase 7 (MMP7) regulates of ciliogenesis and is a biomarker for idiopathic pulmonary fibrosis (IPF) in humans." (PMID 35204783, 2022). "Idiopathic lung fibrosis patient BALF show increased expression of MMPs, with MMP7, MMP8, and MMP9 predominating." (PMID 34512395, 2021). "While the mechanism by which MMP-7 can be involved in the pathophysiology of BA is unclear, MMP-7 has been investigated in other fibrotic pathologies such as renal and idiopathic pulmonary fibrosis." (PMID 33409288, 2020). "In idiopathic pulmonary fibrosis (IPF), immunohistochemical analyses reveal that MMP7 is consistently upregulated." (PMID 31382613, 2019). "MMP-3 and MMP-7, in particular, have been shown to promote the EMT process during the development of pulmonary fibrosis." (PMID 26483688, 2015). "Matrix metalloproteinases (MMPs) are believed to be involved in the pathogenesis of idiopathic pulmonary fibrosis (IPF), and MMP-7 has been described as a useful biomarker for IPF." (PMID 26415518, 2015). "A group of eight proteins has recently been propose as disease progression serum markers in Idiopathic Pulmonary Fibrosis (IPF): KL-6, surfactant protein A, and MMP-7, CCL-18, S100A12, IL-8, ICAM-1 and VCAM-1." (PMID 24216293, 2013).
pulmonary fibrosis (continued). "We also observed increased expression of the Wnt target gene products MMP-7, cyclin D1, VEGF, and AXIN2 that are thought to play an important role in pulmonary fibrosis." (PMID 21935365, 2011). "MMP-7 shRNA alleviated CFA-induced lung inflammation and pulmonary fibrosis in rats." (PMID 40722657, 2025). "Elevated levels of MMP-7, MMP-9, and MMP-13 in severe COVID-19 cases are indicative of ongoing tissue remodeling and inflammation, which could contribute to lung fibrosis and other long-term complications." (PMID 40557167, 2025). "We hypothesized that proteins previously shown to be elevated in patients with pulmonary fibrosis (Amphiregulin, MMP-9, MMP-7, P-selectin, S100A12, and CXCL12) would be elevated in patients who develop fibroproliferative ARDS." (PMID 39106254, 2024). "Previous studies had reported a positive correlation between MMP-7 and other fibrotic diseases, including renal fibrosis and pulmonary fibrosis, but there was no literature has studied the relationship between serum MMP-7 and liver fibrosis in CDCs." (PMID 38914992, 2024). "Additionally, matrix metalloproteinase 1 (MMP1) and matrix metalloproteinase 7 (MMP7) are found in the peripheral blood of individuals with IPF and are highly overexpressed in lung fibrosis and reflect disease progression." (PMID 36056418, 2022). "Currently, there is scarce of evidence suggesting the relationship between motile cilia impairment and the development of pulmonary fibrosis, while several factors dysregulated in IPF have been reported to interfere ciliogenesis or ciliated cell differentiation, such as MMP7." (PMID 35174169, 2021). "This is based on studies in which mice lacking MMP7 were protected from lung fibrosis induced by bleomycin." (PMID 32485920, 2020). "In pulmonary fibrosis, OPN and MMP-7 are hypothesized to engage in a positive feedback loop leading to progressive fibrosis." (PMID 33409288, 2020). "Among the top upregulated DEGs, notable markers included MMP7, a metalloproteinase involved in extracellular matrix (ECM) degradation and biomarker of pulmonary fibrosis; KRT17, an epithelial basal cell marker overexpressed in idiopathic pulmonary fibrosis; and SPP1, a biomarker of IPF." (PMID 38348044, 2024). "As MMP7 is a target of the canonical WNT signaling pathway, it is hypothesized that the canonical WNT signaling pathway will also play a role in the pathogenesis of pulmonary fibrosis." (PMID 31382613, 2019). "However, biomarkers like MUC5B and MMP-7 in bronchoalveolar lavage (BAL) fluid or serum are not specific and cannot be used alone for the diagnosis of pulmonary fibrosis, whereas metabolites in the blood have the potential to renew hope." (PMID 39175820, 2024). "MMP-3-knockout mice and MMP-7-knockout mice do not develop pulmonary fibrosis induced by bleomycin, suggesting that MMP-3 and -7 may also act as mediators of pulmonary fibrosis." (PMID 26415518, 2015).
ovarian carcinoma (61 papers, 2008 to 2025). A malignant neoplasm originating from the surface ovarian epithelium. "In ovarian cancer, the diagnostic usefulness was previously shown for plasma MMP7 and TIMP1 levels in a panel with Ca125 and He4." (PMID 38397798, 2024). "The present study has been conducted to evaluate the association of SNP (181A>G) of the promoter site of the MMP7 (rs1168818) gene with the risk of epithelial ovarian cancer." (PMID 38638796, 2024). "Considering the allele-specific risk, the G allele at the -181 position of the MMP7 promoter region conferred a 1.82 times higher risk for epithelial ovarian cancer." (PMID 38638796, 2024). "The link between the MMP7 -181A/G polymorphism and the risk of ovarian cancer was also statistically significant in the dominant model (AG+GG vs. AA) (OR: 2.12, p = 0.021)." (PMID 38638796, 2024). "Frequency distribution of MMP7 (-181A/G) polymorphism in epithelial ovarian cancer, stratified according to different disease variables." (PMID 38638796, 2024). "Susceptibility to ovarian cancer and MMP7 SNP has been investigated previously in the North China population." (PMID 38638796, 2024). "High blood levels of MMP-7 are associated with the tumor progression of colorectal cancer and positively correlate with the advanced stage of ovarian cancer." (PMID 37686525, 2023). "MMP1 and MMP7 are well-known metalloproteinases to facilitate metastasis and peritoneal dissemination in ovarian cancer, and their overexpression is linked to advanced cancer stages and poor prognosis." (PMID 32823589, 2020). "A thorough understanding of the association between MMP7 SNP and ovarian cancer may help to unveil the role of MMP7 in the etiology of ovarian cancer." (PMID 38638796, 2024). "The potential of MMP7 as a genetic marker was presented as a thesis article, and the present study was conducted to evaluate the association of SNP (-181A>G) of the promoter site of MMP7 in epithelial ovarian cancer patients of the population of eastern India." (PMID 38638796, 2024). "Association of MMP7 (-181A>G) polymorphism with susceptibility to epithelial ovarian cancer." (PMID 38638796, 2024). "Former studies have associated MMP7 with ovarian cancer invasion." (PMID 30142172, 2018). "MMP-7 facilitated the invasion and migration of ovarian tumor cells, indicating its key function in ovarian cancer progression." (PMID 41465326, 2025). "MMP7 promotes the invasion and metastasis of ovarian cancer cells by activating gelatinases and through the MAPK/ERK and JNK pathways." (PMID 40558552, 2025). "Ovarian cancer patients have elevated concentrations of MMP-7, MMP-26, MMP-10 as well as CA125 and HE4 in the total group and subgroups (stage I + II, and III + IV)." (PMID 40565125, 2025). "Immunohistochemistry analysis demonstrated abnormally increased Gli2 and MMP-7 expression levels in benign tumors and ovarian cancer tissues." (PMID 41465326, 2025). "Secondly, the risk of ovarian cancer increased with age in association with MMP3, MMP10, MMP7, TIMP3, POX/PRODH, PYCR1, PYCR3 to indicate degenerative histological changes." (PMID 38397798, 2024). "The same study revealed that SC144 inhibited STAT3 phosphorylation and subsequent expression of survivin, Cyclin-D2 and MMP-7 in a human ovarian cancer cell line." (PMID 36672405, 2023). "Leptin increases MMP-7 expression and subsequent migration and invasion of ovarian cancer cell lines via ObRb, ERK1/2 and JNK1/2 activation signaling pathways and ObRb gene silencing suppresses leptin-induced MMP-7 expression." (PMID 37686525, 2023). "In ovarian cancer, leptin was shown to induce MMP7 (known to degrade collagen type IV, laminin, and fibronectin) and promote invasiveness by activating ERK and JNK pathways." (PMID 35565396, 2022). "Differential expression of ADH1B in ovarian cancer can make cells secrete MMP-7 CD-26 and cathepsin to promote cancer progression." (PMID 35433681, 2022).
ovarian carcinoma (continued). "The authors observed higher concentrations of MMP-7 in epithelial ovarian cancer patients in comparison to healthy controls." (PMID 33916127, 2021). "Leptin-induced ovarian cancer cell invasion via overexpression of MMP7, MMP9, and uPA was reported, and the involvement of the estrogen-independent role of ERα in regulating the phenotype was indicated." (PMID 33799880, 2021). "Results showed overexpression of MMP-7 in both high-grade ovarian cancer and low-grade malignant potential ovarian tumors, and an absence of MMP-7 expression in healthy ovaries." (PMID 32751899, 2020). "Using an integrated analysis of proteomic and transcriptomic data, we have observed the positive regulation of proliferation/stemness factors (e.g., cyclins-CDKs and KIT) and negative regulation of MMPs (e.g., MMP1 and MMP7) by CD83 in ovarian cancer cells." (PMID 32823589, 2020). "Consistent with this transcriptomic observation, proteomics identified that KIT was attenuated, whereas MMP1 and MMP7 were elevated in CD83-KD ovarian cancer cells." (PMID 32823589, 2020). "miR-543 inhibits MMP-7 transcription by binding to the 3’UTRs of MMP-7 mRNA, and it reduces the metastasis of ovarian cancer cells." (PMID 31035447, 2019). "We suggest that ovarian cancer cells stimulate MMP-7 production from tumor macrophages that readily degrade fibulin-5 thereby facilitating tumor progression and invasion." (PMID 29581841, 2018). "MMP-7, which is overexpressed in ovarian cancer cell lines as well as in patient tumor tissue specimens, also promotes invasion through pro-gelatinase activation." (PMID 29861857, 2018). "MMP-7 also promotes the invasion and metastasis of ovarian cancer through mesothelin (MSLN)-activated MAPK/ERK and JNK pathways." (PMID 28538838, 2017). "MMP7 (an oncogene) is also targeted by miR-543 in ovarian cancer; downregulation of miR-543 promotes cancer invasion." (PMID 28589857, 2017). "Mesothelin enhances ovarian cancer invasion by MMP-7 expression through the MAPK (mitogen-activated protein kinase)/ERK (extracellular-signal-regulated kinase) and JNK (c-Jun N-terminal kinase) signal transduction pathways." (PMID 28538838, 2017). "Increased metabolites of 5-lipoxygenase from hypoxic ovarian cancer cells can facilitate the migration and invasion of macrophages, which is achieved via up-regulation of MMP-7 expression through p38 pathway." (PMID 28538838, 2017). "High levels of MMP-9 have been found in human ovarian carcinoma xenografts and overexpression of MMP-7 in ovarian cancer cell lines and cancer surgical specimens." (PMID 22200690, 2012). "Studies on ovarian cancer have shown that the downregulation of Galectin-1 with siRNA-based strategies increases the mRNA levels of E-cadherin and decreases the levels of N-cadherin, MMP7, fibronectin, Snail, and Slug, thereby inhibiting the EMT pathway." (PMID 39996781, 2025). "Moreover, high MMP-7 levels were significantly associated with poor overall survival (OS) and poor PFS in ovarian cancer patients." (PMID 41465326, 2025). "Elevated MMP7 is described in various cancers, including ovarian cancers." (PMID 38638796, 2024). "Specifically, upregulation of MMP7 can be triggered by the interaction between the carboxy-terminal portion of the MUC16/CA125 protein expressed in ovarian cancer cells and mesothelin present on mesothelial cells, leading to an increase in invasive tumor properties and peritoneal carcinomatosis." (PMID 37569592, 2023). "Another study showed that MSLN can enhance the invasion of ovarian cancer by inducing MMP-7 through MAPK/ERK and JNK pathways, blocking the MSLN-related pathway may be a potential strategy to improve the prognosis of ovarian cancer patients." (PMID 34093804, 2021). "MMP-7 may also be a candidate marker for ovarian cancer detection and a possible target for therapeutic intervention." (PMID 32751899, 2020).